Y_RNA (Y RNA )
Gene: Miscellaneous RNA gene on chromosome 7 (136,129,980 to 136,130,081, reverse strand). Ensembl gene ENSG00000206705.
Homologues: Orthologues: chimpanzee Y_RNA (97% identical), macaque Y_RNA (94% identical). Paralogues in human: Y_RNA (86% identical), Y_RNA (84% identical), RNY3 (83% identical), Y_RNA (83% identical), RNY3P1 (82% identical), Y_RNA (82% identical), RNY3P14 (81% identical), Y_RNA (81% identical), RNY3P5 (80% identical), Y_RNA (80% identical), Y_RNA (79% identical), RNY3P16 (78% identical), and 94 more.